PPARG (peroxisome proliferator activated receptor gamma)
Diseases named in the same sentence as PPARG in open-access papers (continued):
Sharing a sentence is not in itself a finding about the gene and the disease.
Obesity (continued). "Therefore, unraveling the interplay between PPARγ and Wnt/β-catenin in MSC fate determination is essential for healthcare, from regenerative medicine to obesity-related issues." (PMID 38292169, 2024). "For instance, the expression of PPARγ is reduced on SAT of pregnant women with obesity compared with non-pregnant women with similar BMI." (PMID 39083072, 2024). "Formononetin, a naturally occurring isoflavone, acts as a non-classical agonist of PPARγ (peroxisome proliferator-activated receptor gamma), which not only treats Alzheimer’s with diabetes but also enhances fat thermogenesis to reduce obesity." (PMID 38167125, 2024). "Li et al106 studied the effects of bisphenol A diglycidyl ether, an antagonist of PPARγ, on an OVX rat model and showed that early treatment with a 30 mg/kg dose of bisphenol A diglycidyl ether reduced bone marrow obesity and stimulated bone formation in ovary-intact and OVX rats." (PMID 38523674, 2024). "The key genes involved in obesity are FTO, MC4R, LEP, LEPR or PPARG." (PMID 39769194, 2024). "The most involved anti-obesity proteins include EGFR, STAT3, JUN, GSK3B, PPARG, and HSP90AA1." (PMID 38674532, 2024). "Hence, the current study was conducted to simultaneously measure the mRNA expression of PPARγ, C/EBPα, LXR, SREBP1c, FAS, and ACC in SAT and VAT from obese women with obesity and those with normal-weight." (PMID 37106328, 2023). "Cumulatively, these findings demonstrate that 6-gingerol exerts its anti-adipogenic and anti-lipogenic effects by suppressing the synergistic activation of PPARγ, C/EBPα, and SREBP-1, thereby contributing to the amelioration of adiposity in HFD-induced obesity." (PMID 37571394, 2023). "When fed with HFHS diet, both WT and KI animals did not develop obesity or insulin resistance, but inhibiting PPARγ S273 phosphorylation induced changes in liver metabolism, mainly related to glycogen metabolism and increased WAT." (PMID 37189379, 2023). "To investigate the molecular basis for the anti-obesity effect of MPE and MSE, we first evaluated whether mango extracts are capable of reducing the level of PPARγ, the master regulator of adipogenesis." (PMID 36982490, 2023). "In the study, the decreased expression of PPARγ in obese WAT trans-activates the uptake transporter Slc1a5; impaired PPARγ in obesity leads to the downregulation of SLC1A5 and decreased adipocyte uptake of glutamine and methionine (two epigenetic modulators), which disrupts Bmal1." (PMID 37626963, 2023). "Additionally, the use of hASCs has enabled the discovery of Thymoquinone’s ability to hinder adipocyte differentiation by suppressing PPARγ and FAS protein expression, positioning it as a promising anti-obesity compound." (PMID 37445596, 2023). "In conclusion, PPARγ is required for mature adipocytes or obese mice, but at the same time, our results show that PPARγ expression does not differ by degree of obesity in adulthood and that obesity due to VitD3 is not achieved by affecting PPARγ expression." (PMID 37823117, 2023). "As expected, lean wild-type animals did not present phosphorylation at PPARγ S273, which is induced by obesity, and no alterations in intraperitoneal insulin (ipITT) and glucose (ipGTT) tolerance tests were detected." (PMID 37189379, 2023). "In addition, mTOR is also involved in the transcription factors SREBPs, PPARγ/PPARα and TFEB in lipid metabolism, which is related to the development of tumours, obesity, and fatty liver." (PMID 36611986, 2023). "Growing evidence demonstrates that appropriate functional antagonism of PPARγ/RXR ameliorates fatty liver, which may be a logical approach to protection against obesity and related diseases." (PMID 37422471, 2023). "Another organophosphate, chlorpyrifos promotes obesity but is not related to the expression of PPARγ, it alters mitochondrial function and thermogenesis in mice." (PMID 36875280, 2023).
Obesity (continued). "Additionally, Hoxa5 transcriptionally activated the PPARγ pathway to promote alternative activation of macrophage and WAT browning, which in turn alleviated obesity-induced chronic inflammation." (PMID 37153549, 2023). "From our data, we found that PPARδ, rather than PPARα or PPARγ, plays an active role in the anti-obesity effect of BBR." (PMID 37511356, 2023). "PPARγ is related to the pathology of many diseases, including obesity, diabetes, atherosclerosis and cancer, and notably, the effects of PPARγ in the tumor occurrence and development are not unifying." (PMID 37976136, 2023). "Adipogenesis is promoted by adipogenesis regulators such as peroxisome proliferator-activated receptor (PPARγ), CCAAT/enhancer binding proteins (C/EBPα), fatty acid synthase (FAS), and CD36, and abnormal regulation of adipogenesis contributes to obesity due to adipocyte dysfunction." (PMID 36838843, 2023). "In addition, onions were found to be effective in suppressing the inflammatory response accompanying obesity by reducing the expression of pro‐inflammatory markers such as CD68, MCP‐1, and PPARγ in adipose tissue." (PMID 37576046, 2023). "Data obtained showed a positive correlation between both genes, however PPARG expression did not correlate with weight nor BMI, indicating a relevant role for ZEB1 in obesity-associated bone alterations." (PMID 36890579, 2023). "Furthermore, the nuclear receptor superfamily of ligand-activated transcription factors includes the peroxisome proliferator-activated receptor gamma (PPAR-γ) agonists which can treat type 2 diabetes and obesity-related insulin resistance." (PMID 36422550, 2022). "Higher levels of SREBP-1c, PPARγ, FAS, and ACC are characteristics of obesity." (PMID 36340916, 2022). "Osteopontin induces brown adipogenesis in cultured preadipocytes through the activation of the PI3K/Akt pathway in a CD44-dependent manner and the downregulation of OPN in WAT of mice exacerbates obesity and inhibits WAT browning via the inhibition of PPARγ-mediated activation of PI3K/Akt signaling." (PMID 35406450, 2022). "Chlorogenic acid could exert anti-diabetic and anti-obesity effects through the AMPK pathway, enhance the expression levels of PPARγ, PRDM16, and PGC-1α in BATs and WATs, increase the insulin production, and inhibit key enzymes in lipid biosynthesis." (PMID 35886989, 2022). "The present results also confirmed the regulatory function of miR-143 and miR-34a in the PPARγ expression and adipogenesis; however, they may not be independent regulators of adipocyte differentiation and/or independent risk factors for the development of obesity." (PMID 35397570, 2022). "Moreover, AMPK is involved in adipocyte differentiation as an upstream regulator of PPARγ, indicating that AMPK activators can exert an anti-obesity effect." (PMID 35563411, 2022). "In addition, several of the CYP2B6-produced 9- and 13-position oxylipins are PPARα and PPARγ activators, providing a putative mechanism for CYP2B6 as an anti-obesity enzyme." (PMID 36520866, 2022). "For example, pharmacological RA has been reported to inhibit adipogenesis by activating Wnt signaling and PPARγ, or promoting the browning of WAT by inducing beige adipose progenitors via RA receptors (RARs), providing a beneficial effect in obesity prevention." (PMID 35794192, 2022). "- Anti-obesity, insulin sensitizer (↓body weight; ↓eWAT; ↓adipocyte size; ↓serum triglyceride; ↓serum insulin; ↓glucose; ↓HOMA-IR) (0.01%, 0.025% of diet, 8 weeks). - Anti adipogenesis in 3T3-L1 cells (↓C/EBPα, PPARγ, FASN, Ap2) (5, 10 μM for 48 h)." (PMID 35769384, 2022). "Therefore, PPARγ has been recognized as a powerful regulator and agonist in WFB and its abnormal expression often leads to the different degrees of obesity syndrome." (PMID 35886989, 2022).
Obesity (continued). "The intervention of 800 mg/kg/d green tea polysaccharides could up-regulate the expressions of CPT-1, down-regulate the expressions of PPARγ, SREBP-1c, FAS, and LXRα, thus significantly reducing the fat index and adipocyte area, and inhibiting mouse obesity." (PMID 35407029, 2022). "On the other hand, the activation of PPARα reduces weight gain, whereas the inhibition of PPARγ decreases lipogenesis; unfortunately, current anti-obesity agents are not selective effectors for each subunit." (PMID 36501129, 2022). "Although there are many controversial studies on the effects of IL-6 on obesity, IL-6 must be the key in the process of energy metabolism and adipogenesis, which may involve pathways like IL-6/STAT3/AMPK and IL-6/STAT3/PPARγ." (PMID 36105933, 2022). "Besides, inhibiting adipogenesis and adipocyte differentiation through downregulation of PPARγ, SREBP-1c, and fatty acid-binding protein (aP2) are other beneficial effects of garlic in obesity treatment." (PMID 37377647, 2022). "This suggests that selective deacetylated PPARγ may be a regulatory switch for the conversion of WAT to BAT, which provides a potential strategy for the treatment of obesity." (PMID 34421358, 2021). "PPARγ and INSR play a vital role in the protective effects of rhein against HFD-induced obesity." (PMID 34516329, 2021). "Additionally, a hybrid molecule acting on peroxisome proliferator-activated receptor gamma (PPARγ) and CB2 receptors was studied as a potential treatment for obesity." (PMID 34681224, 2021). "Phosphorylation of PPARγ S273 by Cdk5 does not affect its adipogenic capacity, but affects many PPARγ target genes that have been shown to be dysregulated in obesity." (PMID 33716977, 2021). "Although strategies targeting CB1R/PPARα have been explored in further depth for the treatment of obesity, the concomitant modulation of CB1R and PPARγ may also be useful for the control of metabolic syndrome and related disorders." (PMID 33498245, 2021). "In mice fed with the high fat diet, SREBP1 increases expression and activity of PPARG and other lipogenic pathways, leading to obesity and non-alcoholic fatty liver disease (NAFLD)." (PMID 33772116, 2021). "Regarding lipid metabolism, the induction of both disorders, arthritis and obesity, alone or combined, promoted a decrease in the mRNA expression of genes involved in lipid accumulation (FAS and PPARγ) and an increase in the expression of genes related to lipolysis, such as HSL and ATGL." (PMID 34721412, 2021). "In addition to PPARγ, the signal transducer and activator of transcription 3 (STAT3) is another important molecular player in obesity." (PMID 34602925, 2021). "In this study, down-regulation of gene expression of PPARγ, C/EBPα, SREBP-1c, aP2, FAS, LPL, and leptin in 3T3-L1 adipocytes by 18KHT01 suggested the potential effect of 18KHT01 on preventing adipogenesis, so prevent obesity." (PMID 34975503, 2021). "PPARγ activation directly upregulated CTSS and MMP-12 expression in the cell types within the PVAT and aorta, accompanied by a reversal of elastin fiber fragmentation and a reduction of elastolytic activity in obesity." (PMID 33781257, 2021). "Furthermore, obesity resistance can be stimulated with a diet that is rich in fat and inhibits the expression of NPY and PPARγ in a rodent model." (PMID 34140894, 2021). "Obesity, as expected, induced insulin resistance in the adipose tissue, seen by a decreased insulin receptor, Glut4 transporter, and PPARγ levels within the visceral adipose tissue, effects not modified when obese animals were exposed to CIH." (PMID 34439481, 2021). "Under overnutrition conditions, PPARγ upregulates high-fat diet (HFD)-dependent NP receptor C (Nprc) expression in adipocytes through long-range distal transcriptional regulation, and thereby attenuates adipocyte NP signaling in obesity." (PMID 34445679, 2021).
Obesity (continued). "A recent study demonstrated that adipocytes PPARγ knockout did not develop adipogenesis, demonstrating the role of this marker in the development of obesity and its complications, such as insulin resistance." (PMID 33430086, 2021). "Beside obesity, miR-27b may be upregulated by human papillomaviruses HPV16 E7 in cervical cancer tissue, which suppresses the expression of PPARγ and increases the level of oncogenic pH regulator, Na+/H+ exchanger isoform 1 (NHE1)." (PMID 34199293, 2021). "Mechanistically, the CGA beneficial anti-obesity effects might be attributed to its ability to decrease C/EBP, PPARγ, and SREBP expression." (PMID 34371900, 2021). "In this work, we aim to figure out whether EA can activate SIRT-1-dependent PPARγ deacetylation pathway and PGC-1α-TFAM-UCP1 pathway to promote the browning of WAT and mitochondria biogenesis, so as to combat obesity." (PMID 33551999, 2020). "LBP suppresses the PA-induced osteoblast apoptosis via the miR-200b-3p/Chrdl1/PPARγ axis to play a protective role for obesity-induced osteoporosis, but miR-200b-3p/Chrdl1/PPARγ is not the only mechanism for LBPs protecting osteoblasts from PA." (PMID 33447177, 2020). "Unlike PPARγ rs1801282, FTO rs9939609 is an intronic variant that was first identified via GWAS to be associated with obesity, conferring risk for T2DM." (PMID 31947684, 2020). "This phosphorylation, performed by the CDK5 at PPARγ S273 (or S245 in isoform 1), does not alter the adipogenic activity of PPARγ, but deregulates a subset of genes, that presented altered expression in obesity and diabetes, such as adiponectin and adipsin." (PMID 33329381, 2020). "Two-way ANOVA showed a significant main effect for postnatal HFD treatment (p < 0.05), but not for maternal HFD/obesity in pPPARγ/PPARγ levels." (PMID 32408716, 2020). "This study related the anti-obesity and anti-adipogenic effects of FXN to its structural characteristics, which promote the downregulation of the expression of key regulatory proteins including PPARγ, C/EBPα, and SREBP1c." (PMID 32260306, 2020). "While activation of PPARγ restores insulin signaling, the impact of PPARγ in VSMCs in obesity-related pulmonary remodelling has not been determined in detail." (PMID 30813929, 2019). "The PPARG/SCAMP3 axis could be important for maintaining a balance between hypertrophic and hyperplastic expansion of adipose tissue in obesity." (PMID 31554889, 2019). "This phosphorylation neither stimulates nor represses PPARγ activation but rather dysregulates a specific set of genes with roles in obesity and diabetes." (PMID 31226166, 2019). "Thus, PPARγ is a promising candidate gene for several metabolic syndromes including T2DM, obesity, and NAFLD." (PMID 30923554, 2019). "An involvement of FABP4 in the pathogenesis of obesity and insulin resistance might be mediated via FABP4-dependent PPARγ inhibition." (PMID 30857223, 2019). "cDC-specific deletion of β-catenin and PPARγ did not affect weight gain, visceral adipose tissue content, or food intake, but enhanced local inflammatory responses and aggravated obesity-induced insulin resistance." (PMID 31191541, 2019). "The expression of FASN gene was also governed by PPARγ and involved in the facilitated conversion of FFA into TG in adipocytes, thus contributing to adipocyte hypertrophy and visceral adiposity in HFD‐fed obesity mice." (PMID 28816006, 2018). "We found that DBZ is a putative PPARγ partial activator capable of preventing insulin resistance, obesity, and atherosclerosis in mice without significant unwanted effects." (PMID 29690611, 2018). "In the past few decades, the role of PPARγ and SERBP-1c in the regulation of obesity and adipocyte differentiation has been highlighted and, hence, PPARγ agonists and antagonists of synthetic or herbal origin have gained wide commercial popularity as therapeutic agents." (PMID 29725353, 2018).
Obesity (continued). "In mutant mice lacking Pparδ via genetic deletion, Pparγ and Pparα are highly expressed in the hypothalamus which would potentiate diet induced obesity." (PMID 29997323, 2018). "However, PPARG-2 rs1801282 may not be associated with obesity and type 2 diabetes mellitus." (PMID 29679223, 2018). "Adipogenic transcription factors such as CEBP/α and PPARγ and their target genes, aP2/FABP4 and FAS, and a complex network of these factors led to lipid accumulation within cells and involved in the development of obesity." (PMID 30200432, 2018). "Therefore, our findings establish that specific targeting of PPARγ, CB2 and HIF pathway with VCE-004.8 could represent a potential therapeutic approach to obesity and T2D, without the harmful effects on adipogenesis and osteoblastogenesis associated with PPARγ full agonists." (PMID 30382123, 2018). "In addition, PPARγ activation in Tregs promotes their accumulation in VAT and protection from obesity-induced insulin resistance." (PMID 29514067, 2018). "Moreover, decreased levels of lipogenic markers PPARγ and C/EBPα after treatment with IBC confirmed the anti-obesity effect of IBC." (PMID 29882838, 2018). "The potential mechanism for this interaction was not very clearly, some studies have reported that both PPARG and CYP1A1 gene polymorphisms were associated with CAD related- risk factors, such as T2DM, obesity and hypertension, and so on." (PMID 28415751, 2017). "As reduction of CD206+ M2-like macrophages did not affect systemic adiposity, CD206+ M2-like ATMs-targeting drugs would not promote obesity, as is observed in the case of PPARγ activators (e.g. thiazolidinedione)." (PMID 28819169, 2017). "Our data indicated that CC treatment could improve obesity, insulin resistance, hyperlipidemia and non-alcoholic fatty liver disease (NAFLD) disease in diet-induced obesity (DIO) mice as a novel PPARγ antagonist." (PMID 28436456, 2017). "Previous studies reported that mice treated with PPARγ partial antagonists such as SR202, GW9662, or BADGE showed decreased TG content in WAT, liver and skeletal muscle, decreased adipocyte size, and increased resistance to HFD-induced obesity." (PMID 28248545, 2017). "We observed that both obesity and PCOS reduce PPARG expression." (PMID 28303117, 2017). "Since the suppression of CHIP may stabilize and activate PPARγ, CHIP suppression may represent a good target for clinical trials for the treatment of diabetes and obesity." (PMID 28059128, 2017). "PPARγ and PGC-1a are known for their important roles in the regulation of efficient energy utilization and oxidative phosphorylation, both of which are reduced in obesity and insulin resistance." (PMID 27379017, 2016). "Derived from these observations, we have coined the so-called “nuclear receptor exhaustion theory,” by which, in an early disease stage, nuclear receptors PPARG and VDR counterbalance the harmful effects that obesity and cancer exert upon the organism, their expression being high." (PMID 27579030, 2016). "It remains unclear how ablation of MTP in A-Mttp−/− mice impacts transcription of PPARγ and protects mice from HFD induced inflammation and obesity." (PMID 26752997, 2016). "Therefore, by targeting the hepatic PPARγ pathway, NRG4 protects against obesity-induced hepatic steatosis." (PMID 27184920, 2016). "Afterwards, possible links between four interrelated actors will be established: PPARG, the vitamin D/VDR system, obesity, and cancer, opening up the door to further investigation and new hypothesis in this fascinating area of research." (PMID 27579030, 2016). "On the basis of the enhanced AA content found in obesity and CRC, we therefore investigated whether this pro-inflammatory PUFA might affect the activation of STAT3 and PPARγ." (PMID 27494857, 2016).